PCDHGC5 (protocadherin gamma subfamily C, 5)
Description:
Potential calcium-dependent cell-adhesion protein. May be involved in the establishment and maintenance of specific neuronal connections in the brain.
Synonyms: PCDH-gamma-C5
Tractability: Antibody: UniProt places it where antibodies can reach, with medium confidence; UniProt predicts a signal peptide or a membrane-spanning region; its Gene Ontology location is reachable by antibodies, with medium confidence; the Human Protein Atlas places it where antibodies can reach.
Gene: Protein-coding gene on chromosome 5 (141,489,081 to 141,512,975, forward strand). Ensembl gene ENSG00000240764.
Subcellular location: Cell membrane
Subcellular location (Human Protein Atlas): Plasma membrane; Vesicles; Cytosol; Nucleoplasm
Gene Ontology:
Molecular function: cell adhesion molecule binding; calcium ion binding
Biological process: cell adhesion; synapse organization; homophilic cell-cell adhesion
Cellular component: plasma membrane; membrane
Genetic constraint (gnomAD): Loss-of-function variants: 25 observed, 61.91 expected, observed/expected ratio (o/e) 0.4, 90% interval 0.29 to 0.56. The synonymous counts are far from expectation, so gnomAD's model fits this gene poorly and the ratio says little. Missense variants: 1,067 observed, 1,277 expected, observed/expected ratio (o/e) 0.84, 90% interval 0.79 to 0.88. Synonymous variants: 434 observed, 537.35 expected, observed/expected ratio (o/e) 0.81, 90% interval 0.75 to 0.87.
Homologues: Orthologues: chimpanzee PCDHGA4 (99% identical), dog PCDHGC5 (93% identical), mouse Pcdhgc5 (93% identical), tropical clawed frog pcdhga11 (52% identical). Paralogues in human: PCDHGC4 (52% identical), PCDHGA5 (49% identical), PCDHGA11 (49% identical), PCDHGA12 (48% identical), PCDHGA4 (48% identical), PCDHGA9 (48% identical), PCDHGA3 (48% identical), PCDHGA2 (48% identical), PCDHGA6 (47% identical), PCDHGA10 (47% identical), PCDHGA7 (47% identical), PCDHGA8 (47% identical), and 49 more.
Diseases named in the same sentence as PCDHGC5 in open-access papers:
PCDHGC5 is named in the same sentence as 8 diseases in open-access papers, as found by Europe PMC text mining. Sharing a sentence is not in itself a finding about the gene and the disease. The quoted sentences say what the papers report.
Alzheimer disease (1 paper, 2020). A progressive, neurodegenerative disease characterized by loss of function and death of nerve cells in several areas of the brain leading to loss of cognitive function such as memory and language. "Recently, a model for Alzheimer’s Disease (AD) was postulated whereby PcdhγC5 could increase inhibitory neurotransmission by enhancing synaptic GABAergic signaling and thus counterbalance the hyperexcitation caused by β-amyloid plaques." (PMID 32694982, 2020).
hypopharyngeal cancer (1 paper, 2025). Carcinoma, predominantly squamous cell, arising from the epithelial cells of the hypopharynx. "For hypopharyngeal cancer, GHRH, UCN3, LCE2B, DDC, and PCDHGC5 were upregulated." (PMID 40255484, 2025).
liver cancer (1 paper, 2022). An epithelial or non-epithelial malignant neoplasm that arises from the liver. "Several studies have shown that PCDH genes are also involved in liver cancer development, including PCDH10, PCDH17, PCDH19, PCDH20, PCDHGC4, and PCDHGC5." (PMID 36230503, 2022).
oropharyngeal cancer (1 paper, 2025). Carcinoma, predominantly squamous cell, arising from the epithelial cells of the oropharynx. "Regarding oropharyngeal cancer, NTS, LCE2B, DDC, PCDHGC5, and MT3 demonstrated increased expression levels." (PMID 40255484, 2025).
pancreatic adenocarcinoma (1 paper, 2019). "An exploratory study of methylation analysis on PCDHAC2, PCDHGC5 and PCDH10 was carried out in 11 pancreatic adenocarcinomas." (PMID 31088413, 2019).
tongue cancer (1 paper, 2025). A malignant neoplasm affecting the tongue. "The findings revealed that, in comparison to their levels in normal tissues, the genes GAL, GHRH, LCE2B, PCDHGC5, and MT3 were notably upregulated in tongue cancer, while NTS was downregulated." (PMID 40255484, 2025).
cancer (3 papers, 2016 to 2019). A tumor composed of atypical neoplastic, often pleomorphic cells that invade other tissues. "Firstly, the survival curves of each C-type isoform indicated that the low methylation values of PCDHGC5 significantly correlate with a decrease of survival probability in the first period of this cancer type." (PMID 31288858, 2019). "PCDHGC5, PCDHAC2, SPTA1, XIRP2 and FLG seemed unrelated with cancer based the reference study." (PMID 27835590, 2016). "Notably, the methylation status of PCDHAC2 and PCDHGC5 were never analyzed before in PDAC, while PCDH10 had been previously studied in PDAC cancer cell lines and one study analyzed this gene in PDAC primary tumors." (PMID 31088413, 2019).
tumor (3 papers, 2018 to 2019). "Differently, PCDHGC4 and PCDHGC5 were commonly hypermethylated in a large variety of tumours." (PMID 31288858, 2019). "As far as PCDHGC5, analysis by COBRA indicated that CpG dinucleotides were methylated in the amplicon analyzed both in tumor and non-neoplastic tissues." (PMID 31088413, 2019).